ETS2 (ETS proto-oncogene 2, transcription factor)
Diseases named in the same sentence as ETS2 in open-access papers (continued):
Sharing a sentence is not in itself a finding about the gene and the disease.
tumor (continued). "An in vivo angiogenesis assay revealed the ability of Ets2 in fibroblasts to promote blood vessel formation in the absence of tumor cells." (PMID 23977064, 2013). "The lack of Ets2 function in the tumor cells shown here is consistent with a previous report from the Oshima lab." (PMID 23977064, 2013). "Specificity was demonstrated by the absence of binding of ERG to the ETS2 promoter in the tumor samples." (PMID 20479932, 2010). "Mechanistically, down-regulation of miR-320 up-regulates v-ets erythroblastosis virus E26 oncogene homolog 2 (ETS2) in PTEN-deleted mammary stromal fibroblasts which activates an oncogenic secretome that reprogrammes the tumor microenvironment and promotes angiogenesis and tumor cell invasion." (PMID 37533462, 2023). "Finally, the highly complex contributions of ETS2 on the one hand, and of primary cilia on the other hand, will obviously complicate the elucidation of the role of CDK10/CycM in tumorigenesis and/or in tumor suppression." (PMID 28178678, 2017). "Results from our ChIP-Seq analysis identified oncogenic c-Myc, Cyclin D1, Ets2, Akt1 and Notch2, pro-inflammatory Hsp90, pro-lymphangiogenic VEGF-C, and pro-apoptotic p27 as novel transcriptional targets of MTA1, revealing its ability to simultaneously activate multiple tumor-promoting pathways." (PMID 26943043, 2016). "Interestingly, the ETS2 gene exhibited a negative correlation between its expression level in tumor tissue and survival (p = 0.046)." (PMID 25575813, 2015). "Functional redundancy of Ets2 with other Ets-family members and/or collaborating transcription factors could account for the lack of a significant effect on tumor growth in epithelial cells." (PMID 23977064, 2013). "ANAPC1 expression level was significantly higher (P = 2 × 10−11), and ETS2 and SORBS1 expression level was significantly lower in tumor tissues than in non-malignant tissues (P = 5 × 10−4 and 1 × 10−8), respectively." (PMID 26893365, 2016). "To identify the functional effect of ANAPC1 rs3814026C>T, ETS2 rs461155A>G, SORBS1 rs7081076C>A and POLR2A rs2071504C>T, we evaluated the relationship between the genotypes of those SNPs and mRNA expression of each gene in tumor and paired non-malignant lung tissues." (PMID 26893365, 2016).
cancer (61 papers, 2004 to 2025). A tumor composed of atypical neoplastic, often pleomorphic cells that invade other tissues. "The aberrant activation of ETS2 is linked to a range of human cancers, underscoring its significance as a promising therapeutic target for ETS2-related diseases." (PMID 37892157, 2023). "The aberrant activation of ETS2 is associated with various human cancers, highlighting its importance as a therapeutic target." (PMID 37892157, 2023). "ETS2 is a transcription factor associated with cancer cell proliferation, due in part to its ability to induce hTERT transcription." (PMID 34445083, 2021). "Misregulation of ETS2 is associated with cancer, and some studies suggest that increased dosage of ETS2 in DS contributes to a reduced risk of cancer." (PMID 22461792, 2012). "The cBioPortal was applied to explore the mutation landscape of ETS1 and ETS2 across cancers." (PMID 36760475, 2023). "However, in our study expected consequence of enhanced ETS2 and cdk10 expressions at active phase of cell migration would be a decreased risk to develop certain types of cancers." (PMID 31413335, 2019). "Furthermore, ETS2 also increases the expression of genes that cause inflammation and promote the growth of cancers." (PMID 26590320, 2015). "Furthermore, the experiments show that high levels of ETS2 are linked with poor outcomes for patients with head and neck squamous cell carcinoma, which is one of the most life-threatening cancers world-wide." (PMID 26590320, 2015). "Pan-cancer analysis utilizing the GEPIA2 database revealed significant variation in ETS2 expression across multiple cancer types." (PMID 40938895, 2025). "Lastly, expression of ERK downstream effectors Ets-1 and Ets-2, known for their cancer promoting roles, was also reduced." (PMID 41209002, 2025). "ETS2 has been proven to exhibit both carcinogenic and suppressive effects in different types of carcinomas." (PMID 40665355, 2025). "Within the SHH pathway, ETS2, a transcription factor involved in tissue development and cancer progression, was slightly more expressed in the capsular zone." (PMID 39167619, 2024). "ETS1 was increased in 12 and decreased in 6 cancers, while ETS2 was increased in 4 and decreased in 13 cancers." (PMID 36760475, 2023). "Considering the frequent dysregulation of ETS2 observed in various cancers, our findings hold significant potential for therapeutic interventions targeting ETS2-related diseases." (PMID 37892157, 2023). "ETS2 was negatively correlated with several immune checkpoint genes in some cancers, including COAD, LUAD, and LUSC." (PMID 36760475, 2023). "Previous research has shown that B4GALT5 is regulated by Ets family transcription factors, including Ets-1 and Ets-2, in cancer cells." (PMID 37628686, 2023). "The expression of BRAF and downstream gene (ETS2) was negatively correlated with methylation levels in various cancers." (PMID 35910024, 2022). "The abnormal expression of Ets2 exists in various cancer types, including prostate, breast, and thyroid cancers." (PMID 36618947, 2022). "ETS2 has also been shown to be a prostate basal cell marker that is overexpressed in some carcinomas." (PMID 31487842, 2019). "H&E staining and fluorescence microscopy showed marked induction of ETS2 and Siah1 in adenocarcinoma samples (n=10) compared to non-cancer tissues (n=10)." (PMID 28481365, 2017). "For example, increased dosage of the Ets2 gene is strongly correlated with protection against intestinal adenomas in ApcMin mice, but is neutral with respect to longevity in the NP-cis cancer model." (PMID 26752700, 2016).
cancer (continued). "This leads to an accumulation of ETS2, which can cause an imbalance in ETS proteins that can lead to deregulation of important target genes involved in cancer progression." (PMID 26871468, 2016). "Taken together, these data identify the control of ETS2 levels as a fundamentally important mechanism for suppressing cancer cell phenotypes." (PMID 26871468, 2016). "In the cancer stem cells, a transcription factor called ETS2 binds to the super-enhancers and reprograms the expression of genes to promote the development of cancer." (PMID 26590320, 2015). "Our added finding that high ELK3 and ETS2 expression correlates with poor prognosis in human SCCs fuels the importance of this family of proteins in these cancers." (PMID 26590320, 2015). "Furthermore, ETS2 has been shown to regulate genes involved in cell proliferation, apoptosis resistance, and angiogenesis, all of which are key hallmarks of cancer." (PMID 40922284, 2025). "Knockdown of the SCC CSC ETS motif gene Ets2 impaired tumorigenesis, whereas expression of a constitutively stabilized form of ETS2 in WT skin led to a cancer-like morphology accompanied by a chromatin landscape and gene expression program that bore striking resemblance to cSCC CSCs." (PMID 39455281, 2025). "Research findings have also indicated that ETS2 may encourage the development of cancer by activating genes like Myc and Cyclin D1 that are involved in cell survival and proliferation." (PMID 40938895, 2025). "WB analysis further verified the decreased protein level of ETS2 in these cancer cell lines." (PMID 40938895, 2025). "ETS1 and ETS2 showed different prognostic values across cancers." (PMID 36760475, 2023). "In conclusion, we demonstrate the roles of ETS1 and ETS2 across cancers." (PMID 36760475, 2023). "ETS1 was increased in several cancers, while ETS2 was decreased in several cancers." (PMID 36760475, 2023). "Nicotine degradation and the heterotrimeric G-protein signaling pathway may also be negatively regulated by ETS2 in both cancers." (PMID 37107558, 2023). "This study explores the expression and prognostic values of ETS1 and ETS2 across cancers." (PMID 36760475, 2023). "However, the prognostic value and immune features of ETS1 and ETS2 across cancers remain poorly understood." (PMID 36760475, 2023). "Understanding the interplay between USP39 and ETS2 may have implications for therapeutic interventions targeting ETS2-related diseases, including cancer, where the dysregulation of ETS2 is frequently observed." (PMID 37892157, 2023). "ETS1 harbored a higher ratio of deep deletion than ETS2 in several cancers." (PMID 36760475, 2023). "Alteration frequencies of ETS1 and ETS2 were both lower than 8% across cancers." (PMID 36760475, 2023). "Similar results were also observed in AGO1, RPS27A, SP1, and ETS2 of several cancers." (PMID 35911954, 2022). "In addition, mutations in the core promoter of the telomerase reverse transcriptase (TERT) gene create a de novo binding site for ETS2, providing a mechanism for cancer-specific telomerase reactivation." (PMID 34261460, 2021). "ETS2 has been initially described as a proto-oncogene frequently found deregulated in many cancers." (PMID 28178678, 2017).
cancer (continued). "KSHV-encoded latent nuclear antigen (LANA), Kaposin B, and K15 have been shown to regulate cells migration and invasion by modulating several cellular cancer-related miRNAs including the miR-221/miR-222 cluster and miR-31, which target ETS2 and ETS1, and the migration inhibitor FAT4, respectively." (PMID 26402907, 2015). "The role of ETS-1 and ETS-2 has been studied for many cancers." (PMID 18958307, 2008). "Thus, ETS1 and ETS2 play different roles in cancer development." (PMID 36760475, 2023). "KEGG pathway analysis also showed that in both cancers, ETS2 may positively regulate T-cell receptor signaling, focal adhesion, Hippo signaling pathway, and transforming growth factor β (TGF-β) signaling, and may negatively influence olfactory regulation and neuroactive ligand–receptor interaction." (PMID 37107558, 2023). "However, ETS1 and ETS2 showed different prognostic values across several cancers." (PMID 36760475, 2023). "However, ETS2 was upregulated in 4 and downregulated in 13 types of cancers." (PMID 36760475, 2023). "V-ets avian erythroblastosis virus E26 oncogene homolog 2 (ETS2) is a protooncogene that regulates numerous cellular functions, including proliferation, apoptosis, differentiation, transformation, and migration, and is overexpressed in various human cancers, including CRC." (PMID 36212157, 2022). "Furthermore, DLEU2 exerts a cancer-promoting function by regulating the expression of ETS2." (PMID 34261460, 2021). "We focused on KLF2 (Krüppel-Like Factor 2), ETS2 (ETS Proto-Oncogene 2), and EBF1 (Early B Cell Factor 1), which are usually deregulated in several cancers, including BC, and have several putative binding sites on the EGFL7 gene." (PMID 39796183, 2025). "Since the transcription of miRNAs with anti-oncogenic activity is often regulated by TFs that are themselves oncosuppressors, we focused on EBF1, ETS2, and KLF2, which are frequently deregulated in cancer, and can bind to the EGFL7/miR-126 promoter regions." (PMID 39796183, 2025). "In the majority of cancers, CELF1 promotes cancer cell proliferation, metastasis, and invasion by activating downstream pathways including AKT/ERK and ETS2." (PMID 38443798, 2024). "For this reason, there has been recent interest in ETS2 inhibitors as a potential means of interrupting the Ras/Raf/MEK/ERK pathway and thus a potential anti-cancer therapy." (PMID 39505854, 2024). "Both ETS1 and ETS2 were favorable prognostic markers in LIHC and KIRC, while they showed different prognostic roles in more cancers." (PMID 36760475, 2023). "We performed a pan-cancer integrated bioinformatic analysis to explore the prognostic potential and immune features of ETS1 and ETS2 across cancers." (PMID 36760475, 2023). "C/EBPα and Ets-2 are the transcription factors which can regulate the expression of UCA1, and the cancer progression can be promoted by UCA1 overexpression through different pathways, including PI3K, AKT, and mTOR-STAT3 signal pathways." (PMID 33680939, 2020). "Although decreased binding of transcription factor ETS2 can modify the expression of the gene, opinions differ on its effect on the level of TERT expression in cancer cells." (PMID 29100407, 2017). "ETS2 is a downstream effector of the RAS/RAF/ERK pathway, which plays a critical role in the development of malignant tumor." (PMID 28724426, 2017). "In cancer, the binding between UCA1 promoter core region and transcription factors or complex (C/EBPα, Ets-2, TAZ/YAP/TEAD and SMAD2/3) can enhance UCA1 promoter activity and gene expression." (PMID 28423704, 2017).
cancer (continued). "To examine the mechanistic basis of Ets2 in ESCC, we determined the effects of Ets2 knockdown on the expression of phosphorylated mTOR (p-mTOR), p70S6K and Prdx1 of ESCC cell in vitro and cancer xenograft mouse model." (PMID 27556183, 2016). "As one of the cell senescence-related genes, ETS2 is involved in regulating multiple key cell signaling pathways in tumors, such as the JAK/STAT, RAS/MAPK, and PI3K/AKT pathways, which perform an essential function in the occurrence and progression of cancer." (PMID 40938895, 2025). "A pan-cancer prognostic analysis of ETS1 and ETS2 was assessed using the KM plotter." (PMID 36760475, 2023). "ETS2 was positively correlated with CD200, NRP1, ICOSLG, and TNFSF15 across several cancers." (PMID 36760475, 2023). "Negative correlation between ETS2 and immune checkpoint genes was observed in multiple cancers, including COAD, LUAD, and LUSC." (PMID 36760475, 2023). "Importantly, members of the Ets transcription factor family, Ets1 and Ets2, contribute to the upregulation of both Snail and ZEB1/2 in cancer cells." (PMID 35451213, 2022). "We found that siRNAs against both Ets1/2 (Ets1 and Ets2), but not either alone, repressed expression of Snail induced by TGF‐β in cancer cells with an active K‐Ras mutation." (PMID 35451213, 2022). "We report herein that Gnetin C, a resveratrol dimer and dietary compound found in the melinjo plant, is more potent than resveratrol and pterostilbene in exerting its anticancer activity in PCa, at least in part, through the inhibition of cancer-promoting co-operation between MTA1 and ETS2." (PMID 31487842, 2019). "Our results do not imply that ETS2 and SIM2 are the only TFs in the HSA21 with a role in oncogenesis because several other TFs, located in the HSA21, also have association with malignancies." (PMID 23343470, 2013). "We have also chosen RUNX1, ETS2, and ERG, a group of genes that are relevant to cancer." (PMID 22461792, 2012). "Furthermore, targeting ETS2 may provide novel therapeutic strategies for IBD by modulating inflammatory pathways, restoring epithelial integrity, and preventing fibrosis and cancer." (PMID 40922284, 2025). "Some factors identified (e.g., NF-κB, STAT3, FOS) are known to be involved for transformation in our model, others (e.g., CEBPB, HIF1a, ETS2, FHL2, TCF7L2, and NFE2L2) have been described as oncogenes in other settings, and some proteins (BHLHE40 and MAFB) have not been well linked to cancer." (PMID 29802342, 2018). "Snail induction by TGF‐β and active Ras is dramatically inhibited using siRNAs against both Ets1 and Ets2 together, but not on their own; in addition, siRNAs against both Ets1 and Ets2 also downregulate the constitutive expression of Snail and ZEB1/2 in cancer cells." (PMID 35451213, 2022).
infection (6 papers, 2017 to 2025). The state of being infected such as from the introduction of a foreign agent such as serum, vaccine, antigenic substance or organism. "EMSA and DNA pull-down assay showed that BMDC infection with LDPm induced Ets1, Ets2, USF1, and USF2 binding to the mouse HAVCR2 promoter." (PMID 37202419, 2023). "Although ETS2 and Siah1 expressed from 1 h p.i., 3 and 6 h infection resulted in highly-induced expression of both of these proteins." (PMID 28481365, 2017). "ETS2 and ETS1, evolutionarily conserved across the metazoans, are required for endothelial cell survival in mammals and play roles in anti‐infection processes in invertebrates." (PMID 40225888, 2025). "Similar to WT STm infection, genes involved in the regulation of immune responses (ATF3, BATF3, ETS2, IRF9, NFκB2, MAFA, TNFAIP3), effector functions, (CCL4, CD200L, CD40, CD72, CD80, IL18) and TLR signaling, (EAF2, TLR15, TRAF3IP2, TOLLIP) were upregulated after ΔprgH STm infection in both models." (PMID 37854334, 2023). "Competition between the viral LTR and endogenous cellular promoter targets for Ets-2 could provide a unifying mechanism behind the autoimmune phenomena observed during HIV infection, present in 1–60% of all infected patients, as well as the role of natural infections in enhancing viral replication." (PMID 29354130, 2017).
cardiovascular disease (2 papers, 2018 to 2024). "Ets2 (ETS2), a transcription factor involved in a wide range of signaling pathways, has been recently linked to cardiovascular disease for its prominent role in the inflammatory phenotype of ECs57." (PMID 29321689, 2018).
bacterial infections (1 paper, 2025). "Further investigation revealed that the transcriptional state of macrophages during serious bacterial infections is significantly enriched for genes induced by ETS2." (PMID 40227609, 2025). "Aside from essential roles in inflammatory disease and bacterial infection, it is possible that ETS2 is involved in other human diseases." (PMID 40227609, 2025).
tumors of digestive system (1 paper, 2023). "ETS2 seemed to be increased mainly in tumors of digestive system including COAD, READ, and STAD, while decreased mainly in tumors of urogenital system including BLCA, KICH, and PRAD." (PMID 36760475, 2023).